FGF7 (fibroblast growth factor 7)
Diseases named in the same sentence as FGF7 in open-access papers (continued):
Sharing a sentence is not in itself a finding about the gene and the disease.
emphysema (3 papers, 2005 to 2021). "Interestingly, recombinant FGF7 has been reported to induce de novo-alveologenesis in the elastase model of emphysema in mice." (PMID 34055804, 2021).
glioma (3 papers, 2013 to 2020). A benign or malignant brain and spinal cord tumor that arises from glial cells (astrocytes, oligodendrocytes, ependymal cells). "Meanwhile, we found FGF7 overexpression protected glioma cells from TMZ cytotoxicity and retrieved the apoptosis promotion function mediated by miR-144." (PMID 32139705, 2020). "The analysis data indicated lower expression of CAV2 predicted longer survival time, but FGF7 level had nothing to do with the glioma prognosis." (PMID 32139705, 2020). "Our data displayed FGF7-Akt regulatory axis inhibited ROS generation and suppressed gliomas apoptosis." (PMID 32139705, 2020). "After identification of the overexpression efficiency of CAV2 and FGF7 by lentivirus infection, glioma cells were transfected with miR-144 as well as overexpression of its targets to validate the glioma cells proliferation and chemotherapeutics sensibility." (PMID 32139705, 2020). "For the mechanism exploration, we detected the ROS generation in TMZ treated glioma cells and found ROS secretion obviously increased in FGF7 transfected cells." (PMID 32139705, 2020). "We also detected the expressions of CAV2 and FGF7 in glioma tissues, which were both much higher than that in normal brain tissue." (PMID 32139705, 2020). "When U251 cells were co-transfected with miR-144 ASO and siCAV2 or siFGF7, FGF7 interfering retrieved gliomas proliferation ability." (PMID 32139705, 2020). "It was the first time to found FGF7-Akt cross link regulating gliomas growth." (PMID 32139705, 2020). "The RT-PCR and western blot were also performed to detected CAV2 and FGF7 levels in glioma cells." (PMID 32139705, 2020). "The data above indicated miR-144 directly targeted CAV2 and FGF7 in glioma cells." (PMID 32139705, 2020). "Our results suggested FGF7, as a target gene of miR-144, could activate glioma cells proliferation and promote cell cycle." (PMID 32139705, 2020). "Besides, the HE staining indicated that miR-144-3p overexpression inhibited the tumorigenesis, while rescue expression of CAV2 or FGF7 promoted the tumor node formation ability of patient-derived glioma cells." (PMID 32139705, 2020). "However, FGF7 level had nothing to do with the glioma prognosis." (PMID 32139705, 2020). "The bioluminescence imaging data showed that miR-144 repressed glioma development obviously, and rescued by CAV2 or FGF7 overexpression." (PMID 32139705, 2020). "The further exploration suggested miR-144’s targets FGF7 and CAV2 modulated gliomas through Akt-ROS regulatory axis and EMT progress, respectively." (PMID 32139705, 2020). "We summarized our conclusions about miR-144 regulating gliomas progression mediated by CAV2 and FGF7 as the schematic diagram exhibiting." (PMID 32139705, 2020). "Meanwhile, since CAV2 and FGF7 are downstream genes of miR-144, other miRNAs targeting CAV2 or FGF7 could be considered as the coordinative genes to suppress glioma development, which perhaps obtain better effect on CAV2-high or FGF7-high gliomas." (PMID 32139705, 2020). "Nine novel functional miRNAs (hsa-miR-129, -136, -145, -155, -181b, -342-5p, -342-3p, -376a/b) in GBM cell lines were validated for their importance in glioma cell growth, and similar effects for six target genes (ROCK1, RHOA, MET, CSF1R, EIF2AK1, FGF7) of these miRNAs were shown functionally." (PMID 23577178, 2013). "To fully understand the molecular mechanisms of miR-144 regulating glioma cells development, we identified miR-144’s targets predicted by several bioinformatic algorithms (Target Scan, PicTar, and miRDB), which suggested CAV2 and FGF7 as candidate target genes of miR-144." (PMID 32139705, 2020).
hepatocellular carcinoma (3 papers, 2010 to 2025). A malignant tumor that arises from hepatocytes. "These CD34-positive MSC exhibited a greater expression of angiogenesis-related genes, including fibroblast growth factor 7 and hepatoma-derived growth factors." (PMID 21151968, 2010). "Mutations in genes such as CHRDL2, STC1, CTGF, GDNF, and FGF7; which are involved in liver fibrosis and inflammation were highlighted, shedding light on their potential role in advancing MASLD towards more severe stages, including liver cirrhosis and hepatocellular carcinoma (HCC)." (PMID 39927143, 2025). "FGF8 and FGF10 are involved in embryonic liver development, FGF7 and FGF9 in repair in response to liver injury, and FGF5, FGF8, FGF9, FGF17, and FGF18 in the development and progression of hepatocellular carcinoma." (PMID 27148532, 2016).
liver fibrosis (3 papers, 2019 to 2021). "Our discovery that IRS2 silencing in HSCs also promoted fibrogenesis while limiting hepatocyte differentiation and FGFR2-IIIb expression in coculture recapitulated the increase in liver fibrosis and reduced Fgf7/Fgfr2-IIIb expression described in Irs2−/− mice during DDC treatment." (PMID 30695023, 2019).
lung adenocarcinoma (3 papers, 2016 to 2022). A carcinoma that arises from the lung and is characterized by the presence of malignant glandular epithelial cells. "FGF9 activates FGFR3 in the respiratory epithelium both during organogenesis and development of lung adenocarcinoma, whereas FGF7 and FGF10 signal through FGFR2b in the airway epithelium." (PMID 35675358, 2022). "Or perhaps it prevents initiation of lung adenocarcinoma, the leading cancer killer, when an AT2 cell divides and a daughter loses contact with the underlying stromal cells that express the Fgf7 and Fgf10 survival signals." (PMID 36414616, 2022). "Using two lung adenocarcinoma (ADC) cell lines, A549 and H1299, we showed that FGF4, but not FGF7, altered cell morphology, promoted EMT-associated protein expression, and enhanced cell proliferation, migration/invasion and colony initiation." (PMID 27677589, 2016).
non-small cell lung carcinoma (3 papers, 2020 to 2022). A group of at least three distinct histological types of lung cancer, including non-small cell squamous cell carcinoma, adenocarcinoma, and large cell carcinoma. "Similarly, functional heterogeneity was also reported in non-small-cell lung cancer, where three CAF subpopulations that differentially expressed hepatocyte growth factor (HGF) and fibroblast growth factor 7 (FGF7), were reported." (PMID 35892828, 2022).
acne (2 papers, 2021 to 2023). An inflammatory process of the sebaceous glands which is characterized by comedones, nodules, papules and/or pustules on the skin. "Consistent with this, prevention of EGFR inhibitor-induced acne by skin irradiation is attributable to FGFR2 downregulation; FGF7-activated FGFR2b causes TGFα-induced EGFR signaling, completing a homeostatic FGFR2-EGFR control loop." (PMID 34007277, 2021). "Expression of FGFR2b-specific ligands FGF7 and FGF10 is androgen dependent, with androgen-induced upregulation of FGF10 being implicated in the pathogenesis of adolescent acne." (PMID 34007277, 2021). "In skin tissues suffering from acne, AR signalling triggers the transcription of two FGFR2 ligands, FGF-7 (also known as keratinocyte growth factor, KGF) and FGF-10, which results in the activation of FGFR2 signalling." (PMID 36803994, 2023). "In the rare seborrhea-acne-hirsutism-alopecia (SAHA) syndrome, acne responds equally well to isotretinoin (which downregulates FGFR2b) and antiandrogens (which block transactivation of FGF7/10)." (PMID 34007277, 2021).
ameloblastoma (2 papers, 2013 to 2020). The most common odontogenic tumor, arising from the epithelial component of the embryonic tooth and usually affecting the molar-ramus region of the mandible or maxilla. "Next, we performed immunohistochemistry to analyze the expression of FGFR1 and FGFR2, the specific receptors of FGF7 and FGF10, in the ameloblastoma specimens and in AM-1 cells." (PMID 24002438, 2013). "We examined 32 cases of ameloblastoma as well as AM-1 cells (an ameloblastoma cell line) and studied the expression of FGF3, FGF7, FGF10 and their specific receptors, namely, FGF receptor (FGFR) 1 and FGFR2." (PMID 24002438, 2013). "In conclusion, this study showed that FGF7 and FGF10 are expressed in ameloblastomas and that they play an important role in the growth of ameloblastomas through the MAPK pathway." (PMID 24002438, 2013). "By western blot analyses, FGF7 and FGF10 were also detected in the ameloblastoma tissues and AM-1 cells." (PMID 24002438, 2013). "Therefore, to examine the effects of FGF7 and FGF10 on the proliferation of ameloblastoma, cell proliferation assays were performed." (PMID 24002438, 2013). "Taken together, FGF7 and FGF10 may play important roles in the proliferation and progression of ameloblastoma." (PMID 24002438, 2013). "In this study, we examined the expression of FGF3, FGF7, FGF10 and their specific receptors in histologically various types of ameloblastoma and analyzed the effect of these growth factors on the proliferation of ameloblastoma using the ameloblastoma cell line AM-1." (PMID 24002438, 2013). "In the present study, we thus hypothesized that FGF3, FGF7 and FGF10 may also affect the proliferation of ameloblastoma cells with odontogenic epithelial characteristics and show some evidences that FGF signaling involved in the ameloblastoma proliferation through MAPK pathway." (PMID 24002438, 2013). "The expression of FGF7, FGF10, FGFR1 and FGFR2 was detected in ameloblastoma cells and AM-1 cells, while that of FGF3 was not." (PMID 24002438, 2013).
Apert syndrome (2 papers, 2009 to 2011). Apert syndrome (AS) is a frequent form of acrocephalosyndactyly, a group of inherited congenital malformation disorders, characterized by craniosynostosis, midface hypoplasia, and finger and toe anomalies and/or syndactyly. "Taken together these data suggest that the mutations associated with Apert syndrome affect affinity for the mesodermally expressed by FGF7 and FGF10, resulting in autocrine signaling." (PMID 20108486, 2009). "Interestingly, the FGFR2c linker domain mutations of Apert syndrome result in enhanced binding of FGF7 and FGF10, both mesenchymally expressed ligands of the FGFR2b isoform and important in limb development." (PMID 20108486, 2009).
bladder cancer (2 papers, 2012 to 2021). "A rat bladder carcinoma cell line, NBT-II, can undergo EMT following addition of several growth factors including FGF1, FGF7, and FGF10 and NBT-II carcinoma cell lines that were rendered autocrine for FGF1 activation had a much higher level of tumorigenicity." (PMID 22701738, 2012).
colon cancer (2 papers, 2020 to 2021). "The suppressive effect of FGF7 on ISG expression and the concomitant increase in DUSP6 expression was also observed with the Caco‐2 colon cancer cell line, which is responsive to FGF7." (PMID 32720440, 2020). "Furthermore, FGF7 or FGF2 suppressed the expression of some ISGs in human lung epithelial cells, colon cancer cells (this study), or in human astrocytes, respectively." (PMID 32720440, 2020).
diabetic retinopathy (2 papers, 2021 to 2023). "It was also confirmed that overexpression of hsa-miR-199a-3p inhibits the proliferation, migration, and invasion of endothelial cells and retinal pericytes of diabetic retinopathy rats through regulating FGF7 via the EGFR/PI3K/AKT pathway." (PMID 36859746, 2023).
endometrial carcinoma (2 papers, 2021 to 2025). A malignant tumor arising from the epithelium that lines the cavity of the uterine body. "FGF7 rapidly activates ERK1/2 signaling in human endometrial carcinoma cells." (PMID 34671204, 2021). "In 2003, ELK1 was identified as a downstream target of Fibroblast growth factor 7 (FGF7; also known as Keratinocyte growth factor, KGF) and Fibroblast growth factor 10 (FGF10; also known as Keratinocyte growth factor 2, KGF2) in human Endometrial carcinoma (EC) cells." (PMID 40862737, 2025).
esophageal cancer (2 papers, 2015 to 2020). A primary or metastatic malignant neoplasm involving the esophagus. "In fact, previous studies have suggested that HGF promotes invasion of ESCC cells and FGF7 (keratinocyte growth factor: KGF) increases the growth rate of esophageal cancer cell lines (TE-8 and TE-11)." (PMID 25884729, 2015).
hypophosphatasia (2 papers, 2021 to 2022). Hypophosphatasia (HPP) is a rare heritable metabolic disorder characterized by defective mineralization of bone and/or teeth in the presence of reduced activity of unfractionated serum alkaline phosphatase (ALP). "Serum FGF7 concentrations are reduced in hyperphosphatemic patients with hypophosphatasia and are elevated in some hypophosphatemic patients with tumor-induced osteomalacia." (PMID 33784965, 2021). "While high FGF23 levels are not evident in non-lethal pediatric hypophosphatasia patients and in fact low levels of the phosphatonin FGF7 were reported in this population, the TNAP−/− mouse model of infantile hypophosphatasia exhibits a very severe and lethal hypophosphatasia phenotype." (PMID 35909501, 2022).
Insulin resistance (2 papers, 2019 to 2024). Increased resistance towards insulin, that is, diminished effectiveness of insulin in reducing blood glucose levels. "Using insulin-resistant mice deficient for insulin receptor substrate 2 (Irs2), we highlight dramatic impairment of proregenerative fibroblast growth factor 7 (Fgf7) signaling between stromal niche cells and LPCs during chronic injury." (PMID 30695023, 2019).
leukemia (2 papers, 2016 to 2023). A malignant (clonal) hematologic disorder, involving hematopoietic stem cells and characterized by the presence of primitive or atypical myeloid or lymphoid cells in the bone marrow and the blood. "Similarly, FGF1 is correlated with chemoresistance in many types of cancer; in particular, FGF7 is linked with hematopoietic stem and progenitor cell support and leukemia-initiating cell growth." (PMID 37932837, 2023).
osteomalacia (2 papers, 2010 to 2021). Disorder caused by an interruption of the mineralization of organic bone matrix leading to bone softening, bone pain, and weakness. "FGF-7 derived from oncogenic osteomalacia–producing tumor cultures was confirmed to be potent inhibitor of phosphate transport in vitro." (PMID 20924490, 2010).
osteosarcoma (2 papers, 2021 to 2024). A usually aggressive malignant bone-forming mesenchymal neoplasm, predominantly affecting adolescents and young adults. "RT-qPCR assay illustrates higher level of FGF7 in four osteosarcoma cell lines (MG-63, HOS, SAOS-2 and U2OS) compared to hFOB." (PMID 34102610, 2021). "Overexpression of FGF7 induced osteosarcoma cell cycle and proliferation, EMT progression and secretion of inflammatory mediators." (PMID 34102610, 2021). "Furthermore, we identified FGF7 is one direct target gene of miR-1303 in osteosarcoma cell." (PMID 34102610, 2021). "Taken together, present study illustrated that BCRT1 is significantly upregulated in osteosarcoma specimens and BCRT1 induces osteosarcoma cell cycle and proliferation and promotes EMT progression and secretion of inflammatory mediators via modulating FGF7 expression." (PMID 34102610, 2021). "Finally, we illustrated that BCRT1 induces osteosarcoma cell cycle and proliferation and promotes EMT progression and inflammatory mediators secretion via modulating FGF7 expression." (PMID 34102610, 2021).
ovarian tumor (2 papers, 2005 to 2024). "The study found high expression levels of FGF7 in normal OSE, suggesting its role as an important autocrine stimulator of OSE growth and its potential involvement in ovarian tumor growth." (PMID 38491511, 2024).
papilloma (2 papers, 2012 to 2013). A benign epithelial neoplasm that projects above the surrounding epithelial surface and consists of villous or arborescent outgrowths of fibrovascular stroma. "We observed that the Vav2/Vav3-dependent Tgfa, Hgf, Fgf7, and Il6 transcripts showed reduced abundance in papillomas derived from Vav2/Vav3-deficient mice when compared to the levels present in control mouse tumors." (PMID 23935450, 2013). "Therefore we hypothesised that in fgf22 knockout mice, where FGF7 and/or FGF10 do not have to compete with FGF22 for receptor binding, it may allow stronger FGF-mediated cytoprotective signalling and, consequently, reduced papilloma formation." (PMID 22737238, 2012).
pulmonary arterial hypertension (2 papers, 2015 to 2020). Pulmonary arterial hypertension (PAH) is a group of diseases characterized by mean pulmonary artery pressure >20 mmHg and elevated pulmonary arterial resistance leading to right heart failure. "Repressing Fgf7 expression with mir-455-3p-1 inhibits pulmonary arterial hypertension by limiting RAS/ERK intracellular signaling." (PMID 33127986, 2020). "Keratinocyte growth factor (KGF or FGF7) can protect newborn rats from death from pulmonary hypertension but not for the decreased septation in >95% oxygen over the first 2 weeks of life." (PMID 26301222, 2015).
rhabdomyosarcoma (2 papers, 2022 to 2024). A rare aggressive malignant mesenchymal neoplasm arising from skeletal muscle. "Additionally, high expression levels of FGFR2 and FGF7 have been associated with increased sensitivity to FGFR inhibitors in fusion-gene-positive rhabdomyosarcoma cell lines." (PMID 38491511, 2024). "The PAX3‐FOXO1 fusion protein in high‐risk rhabdomyosarcomas increases FGFR4, FGFR2, and FGF7 levels." (PMID 34850536, 2022). "Furthermore, patient samples exhibit higher mRNA levels of FGFR2 and FGF7 in fusion‐gene‐positive versus fusion‐gene‐negative rhabdomyosarcomas." (PMID 34850536, 2022).
thyroid cancer (2 papers, 2013 to 2022). "In conclusion, we developed a novel seven-mRNA (CDKN2A, FGF7, CTSB, HAP1, DAPK2, DNAJB1, ITPR1) risk model and nomogram that could help assess the prognosis of patients and guide clinical decision-making and individualized therapy for differentiated thyroid cancer." (PMID 35459137, 2022).
Zika virus infection (2 papers, 2020 to 2022). "For example, FGF7 treatment of keratinocytes enhanced herpes simplex virus-1, lymphochoriomeningitis virus, and Zika virus infection by inhibiting ISG expression." (PMID 35675358, 2022).
ankylosis (1 paper, 2025). Fixation and immobility of a joint. "FGF7, which has been produced in the enthesis by systemic circulating damaged skin–derived IL-17A stimulation, plays a critical role in endochondral ossification and ankylosis." (PMID 39919800, 2025).
biliary tract cancer (1 paper, 2014). "FGF7 (keratinocyte growth factor) has been previously linked to poor prognosis in patients with biliary tract cancer and a small molecule FGFR kinase inhibitor, Ki23057, has demonstrated efficacy in preclinical models." (PMID 24550739, 2014).
cardiomyopathy (1 paper, 2024). A disease of the heart muscle or myocardium proper. "Based on the findings of cell type-specific regulatory activity, the most active TFs in each of the 4 cardiomyopathy fibroblast subpopulations, including NR3C1 (C0 THBS4+ Fibroblasts), KLF4 (C1 LINC01133+ Fibroblasts), FOSB (C2 FGF7+ Fibroblasts), FOS (C3 AGT + Fibroblasts)." (PMID 38799173, 2024).
Cerebral ischemia (1 paper, 2021). Restriction of arterial blood supply to the brain associated with insufficient oxygenation to support the metabolic requirements of the tissue. "FGF-7 protein binds to its natural receptor FGFR2β that leads to angiogenesis and PTX3 is a major mediator of angiogenesis and neurogenesis after cerebral ischemia and has a significant impact on the recovery of lateral exercise function." (PMID 34948061, 2021).
cervical tumor (1 paper, 2008). "The small mass of the mouse cervix and a lack of reagents with high sensitivity and specificity precluded biochemical quantiation of the protein levels of FGF-7 during the course of cervical tumor progression." (PMID 18232728, 2008).